SNRPB2 (small nuclear ribonucleoprotein polypeptide B2)
Description:
Involved in pre-mRNA splicing as component of the spliceosome. Associated with sn-RNP U2, where it contributes to the binding of stem loop IV of U2 snRNA.
Synonyms: Msl1; U2B''
Tractability: Small molecule: a structure with a bound ligand is known. PROTAC: UniProt records ubiquitination sites on it; ubiquitination databases record sites on it; its protein half-life has been measured.
Gene: Protein-coding gene on chromosome 20 (16,729,958 to 16,742,564, forward strand). Ensembl gene ENSG00000125870.
Subcellular location: Nucleus
Subcellular location (Human Protein Atlas): Nuclear speckles; Cytoplasmic bodies
Pathways (Reactome):
Metabolism of RNA: mRNA Polyadenylation; mRNA Splicing - Major Pathway
Chromatin organization: CHD1 and CHD2 subfamily
Disease: Dengue Virus-Host Interactions
Gene Ontology:
Molecular function: protein binding; U1 snRNA binding; nucleic acid binding; RNA binding
Biological process: mRNA splicing, via spliceosome; spliceosomal snRNP assembly; U2-type prespliceosome assembly
Cellular component: catalytic step 2 spliceosome; nuclear speck; nucleus; post-mRNA release spliceosomal complex; post-spliceosomal complex; precatalytic spliceosome; spliceosomal complex; U2 snRNP; U2-type catalytic step 1 spliceosome; U2-type catalytic step 2 spliceosome; U2-type precatalytic spliceosome; U2-type spliceosomal complex; nucleoplasm; spliceosomal snRNP complex
Genetic constraint (gnomAD): Loss-of-function variants: 5 observed, 10.68 expected, observed/expected ratio (o/e) 0.47, 90% interval 0.24 to 0.98. The upper end of that interval is the gene's LOEUF score, 0.98, which puts it in group 4 of 6, group 1 being the genes least tolerant of losing a copy. Missense variants: 85 observed, 107.73 expected, observed/expected ratio (o/e) 0.79, 90% interval 0.66 to 0.94. Synonymous variants: 25 observed, 31.15 expected, observed/expected ratio (o/e) 0.8, 90% interval 0.58 to 1.12.
Homologues: Orthologues: chimpanzee SNRPB2 (99% identical), macaque SNRPB2 (99% identical), pig SNRPB2 (99% identical), dog SNRPB2 (99% identical), rat Snrpb2 (97% identical), guinea pig SNRPB2 (96% identical), rabbit SNRPB2 (96% identical), mouse Snrpb2 (96% identical), tropical clawed frog snrpb2 (83% identical), zebrafish snrpb2 (80% identical), Drosophila melanogaster snf (66% identical), Caenorhabditis elegans rnp-3 (47% identical), and 1 more. Paralogues in human: SNRPA (69% identical).
Diseases named in the same sentence as SNRPB2 in open-access papers:
SNRPB2 is named in the same sentence as 16 diseases in open-access papers, as found by Europe PMC text mining. Sharing a sentence is not in itself a finding about the gene and the disease. The quoted sentences say what the papers report.
esophageal cancer (3 papers, 2025). A primary or metastatic malignant neoplasm involving the esophagus. "By integrating bioinformatics, experimental validation, and clinical correlation analyses, we identified six SFs (CRNKL1, SNRPB2, RBMX2, DDX46, PPWD1, and CFAP20) that are aberrantly overexpressed in esophageal cancer and tightly linked to poor prognosis." (PMID 40282339, 2025). "We found that SNRPB2 mRNA was significantly upregulated in esophageal cancer significantly and correlated with the clinical stage and prognosis." (PMID 40612943, 2025). "While SNRPB2 dysregulation has been observed in various cancers, its role in esophageal cancer (ESCA) remains unclear." (PMID 40303992, 2025). "CRNKL1 and SNRPB2 showed positive correlations with esophageal cancer stemness, suggesting that survival-related SFs may enhance esophageal cancer stemness." (PMID 40282339, 2025). "SNRPB2 may serve as a prognostic biomarker and potential therapeutic target in esophageal cancer." (PMID 40612943, 2025). "We selected two of these SFs (SNRPB2, CRNKL1) and validated their aberrant expression in paired esophageal cancer tissues." (PMID 40282339, 2025). "Exon 11 skipping of CTTN occurred after knockdown of most survival-related SFs (CRNKL1, SNRPB2, PPWD1, RBMX2, and DDX46), while exon 11 inclusion was observed in esophageal cancer in comparison to normal tissue, both in the TCGA database and in our own full-length sequencing data." (PMID 40282339, 2025).
hepatocellular carcinoma (3 papers, 2022 to 2025). A malignant tumor that arises from hepatocytes. "A comprehensive pan-cancer exploration revealing SNRPB2 as a critical RNA splicing regulator with significant prognostic potential in cancer, and SNRPB2 silencing significantly suppresses proliferation and migration of Hepatocellular Carcinoma Cells." (PMID 40303992, 2025). "While primarily studied in hepatocellular carcinoma, SNRPB2 is a novel gene of interest in breast cancer." (PMID 39190284, 2024). "For example, high expression levels of PRPF3 and SNRPB2 were observed in hepatocellular carcinoma and related to poor prognosis." (PMID 35923625, 2022). "Notably, SNRPB2 is markedly upregulated in hepatocellular carcinoma." (PMID 40303992, 2025).
adrenocortical carcinoma (1 paper, 2020). "Finally, we showed the distribution of expression values by copy number for SNRPB2, the gene with the strongest relationship between expression and copy number in adrenocortical carcinoma." (PMID 33119407, 2020).
esophageal squamous cell carcinoma (1 paper, 2025). Esophageal squamous cell carcinoma (ESCC) is a type of esophageal carcinoma (EC) that can affect any part of the esophagus, but is usually located in the upper or middle third. "The relationship between SNRPB2 expression and the clinicopathological features of esophageal squamous cell carcinoma." (PMID 40612943, 2025). "The expression levels of SNRPB2 protein in tumor and para-carcinoma tissues of patients with esophageal squamous cell carcinoma." (PMID 40612943, 2025). "The correlation between SNRPB2 and E2F4 protein expression in esophageal squamous cell carcinoma." (PMID 40612943, 2025).
focal segmental glomerulosclerosis (1 paper, 2025). A renal disorder characterized by sclerotic lesions in the glomeruli. "Pre-transplant antibodies against SNRPB2 were significantly positively associated with late ABMR, prior only associated with the recurrence of focal segmental glomerulosclerosis in kidney transplants." (PMID 40852501, 2025).
lymph node metastasis (1 paper, 2025). "Moreover, high SNRPB2 expression was significantly associated with lymph node metastasis and advanced clinical stage, supporting its potential role in promoting tumor progression." (PMID 40612943, 2025). "Furthermore, the expression levels of SNRPB2 protein in ESCC were significantly correlated with vessel carcinoma embolus and lymph node metastasis, (both P < 0.05) but not with patient age, sex, BMI, smoking or drinking history, tumor location, or nerve invasion (all P > 0.05)." (PMID 40612943, 2025).
malignant thyroid tumors (1 paper, 2022). "Interestingly, the roles of top-ranked discriminatory proteins such as SNRPB2, PRPF3, and LSM8 in other diseases have been investigated for years, although there is limited evidence about the associations between these molecules and malignant thyroid tumors." (PMID 35923625, 2022).
multiple myeloma (1 paper, 2025). "indicate that SNRPB2 is upregulated in multiple myeloma, with patients showing low expression levels of SNRPB2 experiencing higher survival rates, which is consistent with our results." (PMID 40303992, 2025).
triple-negative breast carcinoma (1 paper, 2025). An invasive breast carcinoma which is negative for expression of estrogen receptor (ER), progesterone receptor (PR), and human epidermal growth factor receptor 2 (HER2). "The expression of SNRPB2 was associated with poor prognosis and promoted triple-negative breast cancer progression." (PMID 40303992, 2025). "CD28 within cancer cells also enhances PD-L1 expression by stabilizing CD274 mRNA through its interaction with SNRPB2, driving immune evasion in triple-negative breast cancer." (PMID 40303992, 2025).
cancer (4 papers, 2012 to 2025). A tumor composed of atypical neoplastic, often pleomorphic cells that invade other tissues. "Therefore, 6 of the genes (ENC1, ACAT1, MSTC1, MADCAM1, RPL23 and SNRPB2) were found to be associated with cancer, genetic disorder or reproductive system disease within the same network." (PMID 22280244, 2012). "Moreover, SNRPB2 expression was significantly higher in tumor tissues compared to matched normal tissues across multiple cancer types." (PMID 40612943, 2025). "To comprehensively evaluate the immune-related characteristics of SNRPB2 in ESCA, we conducted a pan-cancer analysis focusing on immune cell infiltration and functional immune signatures." (PMID 40612943, 2025). "We found that CCL15, a chemokine known to promote an immunosuppressive microenvironment and cancer metastasis, was significantly correlated with CRNKL1, SNRPB2, and PPWD1." (PMID 40282339, 2025). "Immunohistochemistry confirmed high SNRPB2 protein expression in ESCC, correlating with vessel carcinoma embolus, lymph node metastasis, clinical stage, and tumor grade." (PMID 40612943, 2025). "To explore the expression of SNRPB2 mRNA in ESCA and normal esophageal tissue samples from TCGA, we analyzed para-carcinoma tissue from patients with ESCA and normal esophageal tissue from tumor-free subjects separately." (PMID 40612943, 2025).
tumor (4 papers, 2024 to 2025). "Immunohistochemistry (IHC) was employed to confirm the expression of the SNRPB2 protein in tumor tissues from clinical samples." (PMID 40303992, 2025). "Conversely, the overexpression of SNRPB2 enhanced the levels of these cell cycle proteins, facilitating the transition of tumor cells from the G1 phase to the S phase and from the G2 phase to the M phase, thereby accelerating tumor cell proliferation." (PMID 40303992, 2025). "Bioinformatic analysis revealed that SNRPB2 expression positively correlated with tumor-infiltrating lymphocytes (TILs), MHC molecules, and multiple chemokines." (PMID 40612943, 2025). "Histological examination using HE staining demonstrated a remarkable decrease in tumor cell density in the SNRPB2 knockdown group." (PMID 40303992, 2025). "In vivo experiments further observed that after inhibiting SNRPB2, the tumor size was significantly reduced, and Ki-67 staining indicated that its proliferative ability was significantly weakened." (PMID 40303992, 2025). "The expression of SNRPB2 was analyzed across 33 tumor types through integration of samples from the GTEx and TCGA databases." (PMID 40303992, 2025). "Increasing evidence indicates that the expression of SNRPB2 is closely related to tumor initiation and progression." (PMID 40303992, 2025). "SNRPB2 plays a critical role in promoting tumor proliferation, migration, invasion, and EMT, highlighting its contribution to the malignant characteristics of ESCA." (PMID 40303992, 2025). "Given that alternative splicing influences immune cell differentiation and activation, and considering the increasingly recognized link between RNA splicing and tumor immune modulation, we also explored the immunological relevance of SNRPB2 in ESCA." (PMID 40612943, 2025). "Mechanistically, SNRPB2 stabilized E2F4 protein by preventing its proteasomal degradation, and E2F4 overexpression reversed the tumor-suppressive effects of SNRPB2 silencing." (PMID 40612943, 2025). "In addition, we utilized scratch assays and Transwell invasion assays to assess the effects of SNRPB2 knockdown on tumor migration and invasion." (PMID 40303992, 2025). "SNRPB2 mRNA was upregulated in ESCA and associated with tumor progression and poor prognosis." (PMID 40612943, 2025). "Interestingly, the expression levels of SNRPB2 protein were positively correlated with high tumor grade and clinical stage (both P < 0.05)." (PMID 40612943, 2025). "In addition, immune-related analyses revealed that SNRPB2 expression was positively correlated with immune cell infiltration and the expression of immunoregulatory genes, suggesting a potential role in modulating the tumor immune microenvironment." (PMID 40612943, 2025). "In addition, the discrepancy between mRNA and protein levels of SNRPB2 across datasets and our clinical cohort may reflect tumor heterogeneity, microenvironmental influences, or post-transcriptional regulatory mechanisms." (PMID 40612943, 2025). "We explored the relationship between survival-related SFs and ploidy, and found that CRNKL1, SNRPB2, RBMX2, and CFAP20 showed significant positive correlations with tumor ploidy." (PMID 40282339, 2025). "In summary, SNRPB2 is significantly upregulated in ESCC and correlates with tumor progression and poor clinical outcome." (PMID 40612943, 2025). "SNRPB2 expression was negatively correlated with levels of tumor-infiltrating CD8+ T cells, suggesting that survival-related SFs may be involved in tumor immune escape and microenvironment changes." (PMID 40282339, 2025).
SNRPB2 also shares sentences with these, for which no sentence is quoted: breast carcinoma (2 papers); genetic disorder (1); lung carcinoma (1); reproductive system disease (1); schizophrenia (1).